CCL11 (C-C motif chemokine ligand 11)
Diseases named in the same sentence as CCL11 in open-access papers (continued):
Sharing a sentence is not in itself a finding about the gene and the disease.
infection (continued). "In the lethal infection, levels of CCL11, interferon- γ and CCL3 all correlated strongly with disease severity." (PMID 24359540, 2013). "In the lethal infection, CCL11, interferon-γ, and CCL3 each strongly correlated with worsening clinical symptoms, including weight loss, diminished oxygen saturation, and increasing Penh." (PMID 24359540, 2013). "The related chemokine CCL11 was significantly up-regulated later in infection mirroring the accumulation of eosinophils in the liver and correlating well with the expression of eosinophil-associated genes." (PMID 20161726, 2010). "WT mice displayed significant increases in Retnla, Il4, Il5, Il13, and Ccl11 (Eotaxin) mRNA expression following infection with N. brasiliensis, while Il25 and the mucin genes Muc5ac and Gob5 were not altered." (PMID 19381262, 2009). "Given the significant impact of CCL11 neutralization on eosinophil recruitment and subsequent bacterial levels, we delved deeper into the dynamics of the eosinophil response during the first eight weeks of persistent STm infection." (PMID 39801515, 2025). "To evaluate the impact of the eosinophil-related chemokine CCL11 during STm infection, we administered a CCL11 neutralizing antibody or an isotype control antibody to mice three days post-infection, with subsequent doses every 3 days until sacrifice at 4 w.p.i.30." (PMID 39801515, 2025). "Investigation into the concentrations of these cytokines, as well as CCL11 and G-CSF, during WT infection demonstrated significant increases both locally and systemically, whereas Δplp1 parasites induced relatively small, if any, increases that resolved by 11 dpi." (PMID 40166190, 2025). "We expected to see classic rise-fall kinetics in the concentrations of CCL11 and IL-5 for the breakthrough infection mice, corresponding with the gradual influx of lung eosinophil counts, but the kinetics for these two analytes did not appear clearly linked to eosinophil numbers." (PMID 41190814, 2025). "Additionally, a substantial increase in IL-17A, CCL11 and IL-3 were observed in the plasma of c-Flip+/–mice on day 2 and day 6 post-infection." (PMID 39038037, 2024). "The decrease of eosinophil levels in PEC was associated with higher levels of CCL11, TSLP, and IL-5 in the peritoneum, suggesting that infected animals increase the levels of these cytokines and chemokine to promote eosinophil differentiation during infection." (PMID 33042162, 2020). "However, in the 4–99 epg infection group, there was a significant increase in CCL11 (p = 0.002) 3 months post-treatment, whereas, CCL5 and CXCL10 were significantly decreased (p = 0.009 and p = 0.002, respectively)." (PMID 30619332, 2018). "Likewise, the frequency of CCL11 (eotaxin-1) was reduced from around 75% in the other infection groups to 55% in individuals with an elevated parasite load (≥100 epg)." (PMID 30619332, 2018). "In the i.n. model, infection by vΔ169 caused enhanced production of several cytokines (IL-2, IL-6 and TNF-α) and chemokines (CCL11, CXCL9 and CXCL10) within 1 day p.i. and subsequent greater recruitment of macrophages and CD4+ and CD8+ T cells and increased lung weight." (PMID 26334635, 2015). "Similarly, the chemokines CCL2 (attracting monocytes), CXCL2 (attracting neutrophils), CCL5 (attracting T cells), CXCL10 (attracting activated T cells, eosinophils), and CCL11 (eosinophils) were elevated during infection with a significant reduction in TLR7 KO mice." (PMID 39769461, 2024). "Based on CCL11 investigations in other pathological conditions and its role in eosinophil chemotaxis to the infection site, it could be hypothesised that this chemokine could be involved in eosinophil recruitment to contribute to parasite elimination and tissue remodelling following treatment." (PMID 33059754, 2020).
infection (continued). "In urine, we found increases in IL-1RA, G-CSF, and chemokines CXCL10, CCL4, CCL11, GROα/β/γ, and IL-8/CXCL8, with IL-1RA and CCL4 showing direct correlation with the degree of pyuria at the time of infection." (PMID 41810365, 2026). "It therefore appears that CCL11 and CCL17 reach their highest levels during the early phase of infection, acting as rapid attractants for eosinophils to the site of inflammation." (PMID 40918106, 2025). "In this USUV infection model, cytokines CXCL10, CCL11, CXCL1, and G-CSF peaked in the brain at later time points." (PMID 41472308, 2025). "Infection with this bacterium was shown to increase the production of IFN-γ, TNF-α, and chemokines such as CCL3, CCL4, CCL5, CCL11, and CXCL1." (PMID 38139161, 2023). "In response to inflammatory stimuli to the chemokines CCL11 (eotaxin-1), CCL24 (eotaxin-2), and CCL5 (RANTES), eosinophils migrate to inflamed tissues or to sites of infection where their survival is prolonged." (PMID 37483591, 2023). "Network analysis of serum mediators performed between 28 and 35 days after initial infection in the usual care study group shows persistent IFN-α2a, CCL11, and CCL2." (PMID 35397798, 2022). "Expression levels of IL-1β, RANTES (CCL5), IP-10, eotaxin (CCL11), KC, MCP-1, MIP-2, and MIG were significantly lower in MET + PCV vs. control + PCV group at 7 days post-infection (all p < 0.05)." (PMID 35821804, 2022). "Several chemokines were induced quickly in the early phase (day 2 p.i.)and maintained at a rather high level through the first week of infection, including CCL2, CCL3, CCL4, CCL7, CXCL10, IL-6, IFN-γ, CCL11, CCL5, TNF-α, CXCL1, IL-4, IL-12p70." (PMID 34379705, 2021). "At pre-treatment, the chemokines CCL5, CCL11, and CCL17 were readily detected in all infection groups and the frequencies of responders were similar to the egg-negative individuals." (PMID 30619332, 2018). "Post-infection, the CCR3 ligand, CCL11, was upregulated at the transcript level in peritoneal cells and relative transcripts were significantly impaired in BmL3-infected IL-4Rα-/- mice." (PMID 29547639, 2018). "Only GJ18 experienced any systemic pro-inflammatory response with transiently increased plasma concentrations of IL-12, CXCL8, and MIF by day 1 to 2 post-infection that rapidly resolved to baseline and later increases in CCL2 and CCL11." (PMID 29259582, 2017). "Contrary to the pattern of Th1-type response gene expression, 5 of the 14 Th2 type response genes (IL5, CCL11, CCR3, IL1RA and GATA3) were significantly downregulated at 2, 4, 8 and 12 weeks post-infection." (PMID 23448601, 2013). "On the other hand, four days after infection, TLR3−/− mice showed significantly increased mRNA expression of IL-6, CCL2, CCL11 and IFN-λ." (PMID 21637773, 2011). "Two chemokines in analyte cluster 2, EGF and CCL11, were also uniformly expressed by all patient clusters independent of infection outcome and are also involved in cell recruitment." (PMID 39966757, 2025). "In the striatum, we also see clustering within the fentanyl-treated groups based on infection status: EcoHIV-infected mice treated with fentanyl had higher concentrations of CCL2, CCL4, CCL5, and CCL11 but lower levels of CCL3 and CXCL10 than the uninfected, fentanyl-treated animals." (PMID 40447886, 2025). "Conversely, CpG sites related to Slc11a1, Havcr2, Ccl11, Ccl12, Sirt1, Ifng, Ccl3, Ror2, and Trem2 maintained lower methylation levels throughout the infection compared to noninfected samples." (PMID 40170749, 2025). "However, only a few inflammatory mediators remained elevated at 28 days post-infection in the hippocampus in the B.1.351 model (IL-6) and in the CSF in the AAV model at 7 weeks post-infection (CXCL10, CCL11)." (PMID 39861887, 2025). "CCL-2 exhibited heightened levels on day 1 post-infection, while IL-1β, IL-13 and CCL11 showed increased levels on both day 1 and 4 post-infection, as compared to the non-infected group." (PMID 39038037, 2024).
infection (continued). "We did not observe basophils or eosinophils histologically during infection with C. violaceum, and this was again supported by the absence or low expression of chemokines involved in trafficking of these cell types (i.e. Ccl11, Ccl24, and Ccl26)." (PMID 38352492, 2024). "Similarly, we observed significant increases in IL-17, G-CSF, CXCL1, CCL2, CCL3, CCL4, and CCL11 production in 5-LO−/− mice, compared to C57BL/6 mice, at day 7 post-infection." (PMID 39082787, 2024). "Though most of these genes were upregulated at 7 dpi after Delta infection, we did not see CCL11 upregulation in mature hamster brains after either Omicron BA.2 or Delta infection." (PMID 37122119, 2023). "However, at 30 days post-infection, TNF-α, IL-6, KC, CCL3, CCL2, CCL20, CXCL11, CCL11), CCL27, CXCL5, CXCL12 and CCL5 were all significantly higher in the BAL fluid of Duox1 KO compared to WT mice." (PMID 36936954, 2023). "On a systems level, elevated concentrations of the cytokine CCL11 were detected in individuals suffering from Long COVID as compared with those who experienced no symptoms following infection." (PMID 37038497, 2023). "S. oralis infections as single species caused a significant increase in the expression of IL-1α, IL-6, IL-12 (p40), CXCL1/KC, CCL5/RANTES, and CCL11 compared to infection without implants." (PMID 35203495, 2022). "The expression levels of IL-1β and CCL11 in the infection group were lower than those of the non-infected group at 48 hours post-infection, suggesting that these genes were strongly suppressed by tetrathyridium infection." (PMID 33048942, 2020). "The expression of CCL11/eotaxin-1 mRNA was not significantly elevated 24 h after infection and was not different between control and MDA5−/− mice." (PMID 21637773, 2011). "This further, may account for the significant negative correlation between Na infection intensity and CCL11 levels in the group infected with hookworm only." (PMID 33604551, 2019). "While we did not directly assess whether CCL11 levels would rebound at later time points after treatment, uninfected, untreated animals displayed a marked increase in this cytokine before rapidly succumbing to infection." (PMID 41472308, 2025). "The concentration of certain cytokines, including CCL11, IL-1β, IL-5 and CXCL2 were similar between infected and control mice throughout the course of infection (not shown)." (PMID 35812400, 2022). "On day 7 p.i., in addition to chemokines upregulated on day 3 p.i., lethal infection further induced higher expression of CCL2, CCL6, CCL11, CCL19, CCR7, CXCR1, and CXCL11 compared to nonlethal infection." (PMID 23526993, 2013). "Therefore, the results of serum CCL11 and CCL17 concentrations did not support previous findings that these chemokines could also be used as infection markers in individuals with diminished parasite loads." (PMID 30619332, 2018).
cancer (57 papers, 2007 to 2025). A tumor composed of atypical neoplastic, often pleomorphic cells that invade other tissues. "Particularly noteworthy is our identification of TGFB1 and CCL11 as risk‐promoting factors (OR = 1.173, p = 0.020; OR = 1.192, p = 0.003), which aligns with existing knowledge of their biological functions in cancer development." (PMID 40682474, 2025). "Elevated levels of CCL11 have been reported in some cancer types, where they are associated with a poor prognosis." (PMID 35804913, 2022). "Collectively, these results showed that CCL11 was overexpressed in CAFs, implicating that CCL11 was associated with CAF-induced cancer behaviors." (PMID 35804913, 2022). "CCL11 has been reported as a diagnostic or prognostic marker in cancers." (PMID 35804913, 2022). "Validation of these data exhibited that chemokines involved in promoting macrophage polarization and cancer metastasis, including CCL11 and CCL26, were stimulated by Wnt3a signaling and their expression was abrogated by treatment with rSFRP1." (PMID 38554160, 2024). "As CCL11 is a secreted protein, we confirmed these finding as well as the cancer cell origin of this chemokine by staining for Ccl11 and Krt19 using RNA fluorescence in situ hybridization." (PMID 38195933, 2024). "This intriguing and novel finding was validated in the present study by showing that the functional CAF-induced CCL11 plays a driving role in cancer behaviors via induction of EMT and enhancing CSC-like properties." (PMID 35804913, 2022). "CCL11 signaling regulates the TME impacting cancer progression; however, its specific mechanism of action for OSCC or other kinds of HNSCC has not been reported." (PMID 35875097, 2022). "This makes us think that NF-κB regulation and activation of CCL11 can promote cancer angiogenesis and affect the prognosis of HCC." (PMID 36397950, 2022). "Here, we provide a clear step-by-step demonstration of CCL11 as a critical mediator in CAF-induced cancer invasiveness." (PMID 35804913, 2022). "The diagrammatic illustrations of three sequential steps demonstrate our proposal to explain the major mechanism of how CAF-induced CCL11/CCR3 signaling in TME contributes to cancer behavior." (PMID 35804913, 2022). "To understand the CCL11-mediated crosstalk between cancer cells and CAFs at the molecular level, we investigated if the paracrine effects of CCL11 effect the expression of the CSC-like properties of HNCs." (PMID 35804913, 2022). "Chemokine ligand 11 (CCL11), also known as eotaxin-1, is involved in cancer cell migration and invasion." (PMID 35804913, 2022). "Treatment with rCCL11 induced the EMT phenotype in our cells, suggesting that CCL11 is a novel mediator in CAF-induced cancer aggressiveness through the induction of EMT." (PMID 35804913, 2022). "Their recruitment in response to the cancer-cell secreted alarmin IL-33, is mediated by the chemokine CCL11, and enhanced with the administration of sitagliptin, an inhibitor of dipeptidyl peptidase DPP4 (CD26) that cleaves CCL11." (PMID 33815418, 2021). "Among the works found, only one publication assessed the concentration of CCL11 in patients with colorectal cancer." (PMID 33401527, 2021). "Some researchers revealed that CCL11 (C-C motif chemokine ligand 11, eotaxin-1) concentrations differed between the control and tested groups indicating their possible usefulness in cancer detection." (PMID 33401527, 2021). "Among them, CXCL10, CXCL11 and CCL11 are chemokines that direct cell migration in development, immunity, inflammation and cancer." (PMID 28938587, 2017). "In addition to its allergic inflammation role, CCL11 exhibits context-dependent dual functions in relation to cancer progression." (PMID 40429807, 2025). "To explore the mechanism of action of CCL11 in cancers, we reviewed previous reports." (PMID 38305920, 2024). "This suggests a complex regulatory role for CCL11 within the TME of malignant tumors." (PMID 38305920, 2024).
cancer (continued). "Activation of ERK MAPK by CCL11 mediates apoptosis resistance in cancer cells." (PMID 36397950, 2022). "Furthermore, neutralization of CCL11 activity reversed the aggressive phenotype of CAF-induced cancer cells." (PMID 35804913, 2022). "CCL11 overexpression in the CAF-culture medium suggests that CCL11 might be critical for CAF-induced cancer aggressiveness." (PMID 35804913, 2022). "For precision medicine-based clinical practice, modulating the TME by targeting the CCL11/CCR3 signaling circuit may attenuate the aggressiveness of cancer cells and offer a novel therapeutic strategy to improve the prognosis in patients with HNC." (PMID 35804913, 2022). "Neutralization of CAF-induced CCL11 reversed the aggressive phenotype of cancer cells." (PMID 35804913, 2022). "Until now, CCL11 implication in cancer progression has been scarcely investigated." (PMID 33608009, 2021). "In addition, CCL11 promotes angiogenesis, and its overexpression is closely related to the occurrence and progression of cancer." (PMID 34513705, 2021). "On a basis of the results obtained so far, it may be suspected that eotaxin-1 (CCL11) could be a preferred eotaxin for cancer monitoring in the future." (PMID 33401527, 2021). "In addition, they chose to examine the levels of CCL11 in serum, while our data demonstrated it was the cancer cells that secreted CCL11." (PMID 27119233, 2016). "To summarize, CCL11 might be a potent T cell enhancer against cancer." (PMID 38459592, 2024). "We examined whether CAF-induced CCL11 promoted cancer cell aggressiveness by inducing EMT." (PMID 35804913, 2022). "Furthermore, we also studied whether CC chemokine receptor 3 (CCR3), the main corresponding receptor of CCL11, is directly involved in signal transduction resulting in cancer progression." (PMID 35804913, 2022). "In addition, the higher ratios of IFNα2 to Th2 cytokines, including IFNα2/IL4, IFNα2/IL10, IFNα2/CCL2, IFNα2/CCL7, IFNα2/CCL11, and IFNα2/TNFα, were associated with increased odds of ER negative vs. ER positive cancer." (PMID 24473087, 2014). "Increased levels of CX3CL1 (from 75 to 115 pg/mL, p = 0.0056) and CCL11 (from 13 to 20 pg/mL, p = 0.0077) were also observed in S + M2, which can be explained by the interaction of 4T1/GFP cancer cells with the M2 activation factor IL-4." (PMID 37445941, 2023). "On the other hand, CCL11 (Eotaxin), HGF, TIMP‐1 and MCP‐1 (CCL2) were secreted more by the fibroblasts compared to prostate epithelial/cancer cells." (PMID 36608258, 2023). "In our result, we verified the existence of the main corresponding receptor of CCL11, CCR3, that is directly involved in signaling transduction and cancer progression by confocal microscopy and immunohistochemistry." (PMID 35804913, 2022). "We demonstrated the role of CCL11 in the CAF-promoted aggressiveness of cancer cells, as well as the mechanisms involved in the interactions between cancer cells and fibroblasts." (PMID 35804913, 2022). "Thanks to IL-6 autocrine and paracrine stimulus, CAFs upregulate VEGF, activate the JAK2/STAT3 pathway, express MCP-1, CCL11/8/20, CXCL5 and IL-9 for cancer cell invasion, growth and survival." (PMID 34944856, 2021). "Encouragingly, many studies correlating with the effects of CCL2, CCL11, and CCL21 on anti-cancer properties focus on their relationships with T cell functions." (PMID 31754081, 2019). "We then demonstrated in vitro that both CCL11 and its receptor, CCR3, were overexpressed and promoted the proliferation, migration and invasion of cancer cells." (PMID 27119233, 2016). "Pan-cancer analysis of the relationship between OBSCN expression and chemokines revealed a significant negative correlation between OBSCN expression and a variety of chemokines, including CXCL10, CXCL11, CCL11, CCL21, and CCL23." (PMID 40149008, 2025). "However, we were most intrigued by our CCL11 and CCL26 results because both of these chemokines are involved in promoting macrophage polarization and cancer metastasis." (PMID 38554160, 2024).